RSPO2 (R-spondin 2)
Diseases named in the same sentence as RSPO2 in open-access papers (continued):
Sharing a sentence is not in itself a finding about the gene and the disease.
diarrheal disease (1 paper, 2018). The condition of having at least three loose or liquid bowel movements each day. "While most mouse strains suffer relatively mild, self-limiting inflammation following C. rodentium infection, we have shown that susceptible mouse strains suffer fatal diarrheal disease due to robust Rspo2 induction during infection." (PMID 29339782, 2018). "We previously discovered a novel pathway in susceptible mice (e.g. C3H/HeOuJ, AKR, FVB) that leads to the development of fatal diarrheal disease during C. rodentium infection through Rspo2-mediated disruption of intestinal homeostasis." (PMID 29339782, 2018).
endometrioid adenocarcinoma (1 paper, 2021). An adenocarcinoma characterized by the presence of malignant glandular epithelial cells resembling endometrial cells. "Interestingly, a functionally relevant RSPO2 gene fusion/microdeletion was discovered in the endometrioid adenocarcinoma case." (PMID 34200508, 2021).
glioma (1 paper, 2018). A benign or malignant brain and spinal cord tumor that arises from glial cells (astrocytes, oligodendrocytes, ependymal cells). "Noticeably, RSPO2 is almost undetectable in glial cells, which are the cell of origin of glioma." (PMID 30337838, 2018).
infertile (1 paper, 2017). "Rspo2 heterozygous deficient female mice become infertile around 4 months of age mimicking primary ovarian insufficiency (POI)." (PMID 28743298, 2017). "This infertile phenotype associated with the oocyte Rspo2 expression and follicular growth function led us to consider this gene as a possible candidate gene in POI." (PMID 28743298, 2017).
injury (1 paper, 2023). Damage inflicted on the body as the direct or indirect result of an external force, with or without disruption of structural continuity. "Previous studies had demonstrated that Rspo2 could mitigate inflammation response in IL-1β-treated chondrocytes and regulate inflammation response in acute ozone-induced lung injury." (PMID 37946278, 2023).
intestinal tumours (1 paper, 2023). "As a result of these fusion mutations, high levels of RSPO2 and RSPO3 are detected in tumours harbouring these mutations, and indeed, mice harbouring Rspo2 or Rspo3 fusion mutations develop intestinal tumours." (PMID 37048063, 2023).
large cell lung carcinoma (1 paper, 2020). "We next investigated RSPO2 deficiency in H1581 cells, a human large cell lung carcinoma cell line that expresses high levels of RSPO2." (PMID 33149137, 2020).
mental disorder (1 paper, 2024). A disease that has its basis in the disruption of mental process. "These CpG hits map to genes in systems that have in part been previously implied in depressive or other mental disorder phenotypes: R-Spondin 2 has been implied in the development of midbrain dopaminergic neurons and has been linked to fear extinction processes in the amygdala." (PMID 39367879, 2024).
ovarian carcinoma (1 paper, 2022). A malignant neoplasm originating from the surface ovarian epithelium. "Collectively, these results suggest that the expression of RSPO2 is elevated in ovarian cancer and associated with poor prognosis in patients." (PMID 36217544, 2022). "Kaplan-Meier analysis of another ovarian cancer dataset (GSE26193) also showed a significant association between high RSPO2 expression and poor survival." (PMID 36217544, 2022). "Based on our results, we proposed a novel Wnt-independent mechanism underlying the promotive effect of RSPO2 on ovarian cancer progression." (PMID 36217544, 2022). "Moreover, mining of the ovarian cancer cohort in the TCGA database showed that high RSPO2 expression was associated with a lower survival rate in patients with ovarian cancer." (PMID 36217544, 2022). "In addition, further investigations are required to elucidate the underlying mechanism of how RSPO2 expression is upregulated in ovarian cancer tissues." (PMID 36217544, 2022). "Our data suggested that RSPO2-mediated hyperactivation of Src/Akt participates in cell cycle progression, thus providing a growth advantage to ovarian cancer cells." (PMID 36217544, 2022). "In this study, we found that overexpression of RSPO2 increased the total amounts of integrin-αv/β3 in ovarian cancer cells by preventing their ubiquitination and degradation." (PMID 36217544, 2022). "Mechanistically, we revealed that RSPO2 promotes ovarian cancer progression by enhancing FAK/Src signaling cascades via two unexpected actions." (PMID 36217544, 2022). "Taken together, these sets of data suggest that RSPO2 promotes ovarian cancer progression through the activation of FAK/Src signaling cascades." (PMID 36217544, 2022). "Taken together, these results strongly suggest that RSPO2 functions as an oncogene in ovarian cancer progression by promoting tumor cell growth and metastasis." (PMID 36217544, 2022). "Here, we demonstrated that the pharmacological inhibition of RSPO2-induced FAK/Src activation significantly impaired ovarian cancer cell growth and migration, suggesting that the RSPO2/FAK/Src axis is a druggable target." (PMID 36217544, 2022). "Together, these results indicate that RSPO2 plays a promotive role in ovarian cancer cell growth in vitro." (PMID 36217544, 2022). "We demonstrated that RSPO2 enhanced the malignant biological behaviors of ovarian cancer cells, including proliferation, migration, and invasion, as well as their ability to adhere to the extracellular matrix in vitro." (PMID 36217544, 2022). "Here, we reported that RSPO2 promoted the growth and metastasis of ovarian cancer through the activation of FAK/Src signaling cascades." (PMID 36217544, 2022). "Our results suggested that integrin-mediated FAK/Src signaling activation plays a critical role in RSPO2-promoted ovarian cancer progression." (PMID 36217544, 2022). "Next, we measured RSPO2 protein expression in ovarian cancer specimens by tissue microarray analysis." (PMID 36217544, 2022). "In this study, we demonstrated that RSPO2 plays an oncogenic role in ovarian cancer progression by promoting the growth and metastasis of ovarian cancer cells." (PMID 36217544, 2022). "Via FAK/Src inhibitor treatment and functional rescue experiments, we validated the critical role of FAK/Src signaling activation in RSPO2-promoted ovarian cancer progression." (PMID 36217544, 2022). "Morphologically, overexpression of RSPO2 promoted the transformation of most ovarian cancer cells from a round (epithelial phenotype) to a spindle shape (mesenchymal phenotype)." (PMID 36217544, 2022). "We elucidated a Wnt-independent mechanism by which RSPO2 promotes ovarian cancer cell growth and metastasis through the potentiation of FAK/Src signaling." (PMID 36217544, 2022). "To elucidate the Wnt-independent mechanisms by which RSPO2 promotes ovarian cancer progression, we compared the gene expression profiles of parental and RSPO2-overexpressing A2780 cells through transcriptomic sequencing." (PMID 36217544, 2022).
ovarian carcinoma (continued). "Furthermore, treatment with Src and FAK inhibitors abrogated the promotive effect of RSPO2 on the proliferation and the migration of ovarian cancer cells." (PMID 36217544, 2022). "Consistent with the migration-promoting function of RSPO2 in vitro, stable overexpression of RSPO2 markedly promoted metastatic colonization of ovarian cancer cells in an orthotopic mouse model, including increases in the number of metastatic nodules, tumor size, and tumor weight." (PMID 36217544, 2022). "RSPO2 overexpression also increased motility in both ovarian cancer cell lines." (PMID 36217544, 2022). "Our study suggests that the disruption of RSPO2/FAK/Src signaling cascades may be a therapeutic strategy for aggressive ovarian cancer." (PMID 36217544, 2022). "To determine the specificity of RSPO2 on tumor growth, we next screened two siRNAs (siRS2-1# and siRS2-2#) that can effectively target RSPO2 in two ovarian cancer cell lines, and then used the most effective interference sequence siRS2-2# to construct the lentiviral vector (shRS2)." (PMID 36217544, 2022). "In this study, we investigated the role of RSPO2 in ovarian cancer progression." (PMID 36217544, 2022). "R-spondin 2 (RSPO2) drives the potentiation of Wnt signaling and is implicated in tumorigenesis in multiple cancers, but its role in ovarian cancer has not been investigated." (PMID 36217544, 2022). "In summary, we demonstrated that RSPO2 acts as an oncogene in ovarian cancer progression." (PMID 36217544, 2022). "To determine whether the expression of RSPO2 is dysregulated in ovarian cancer, we first examined the expression of RSPO2 in multiple ovarian cancer cell lines by qRT-PCR." (PMID 36217544, 2022). "However, the biological function of RSPO2 in ovarian cancer progression remains unexplored." (PMID 36217544, 2022). "However, little is known about the function of RSPO2 in ovarian cancer." (PMID 36217544, 2022). "Second, RSPO2 directly bound to integrin β3 as a ligand and enhanced the stability of integrins, and both actions potentiated autoactivation of FAK and/or Src in ovarian cancer cells." (PMID 36217544, 2022). "Taken together; these results suggest that RSPO2 prevents the endocytosis and lysosome-mediated degradation of LGR4 in ovarian cancer cells." (PMID 36217544, 2022). "In the current study, we provided evidence that independent of Wnt signaling, RSPO2 promotes ovarian cancer progression by potentiating FAK/Src signaling cascades." (PMID 36217544, 2022). "Second, RSPO2 is directly bound to integrin β3 as a ligand and thus increased the stability of integrins, and both actions potentiate the autoactivation of FAK and/or Src in ovarian cancer cells." (PMID 36217544, 2022). "Our study highlights the importance of RSPO2 in ovarian tumor progression and suggests that targeting RSPO2/FAK/Src cascades may constitute potential approaches to inhibit the progression of aggressive ovarian cancer." (PMID 36217544, 2022). "RSPO2 did not affect the mRNA level of LGR4 in either of these ovarian cancer cell lines." (PMID 36217544, 2022).
ovarian tumor (1 paper, 2022). "RSPO2 expression was increased in ovarian tumors and was associated with poor prognosis in patients." (PMID 36217544, 2022). "Consistent with its oncogenic function, the RSPO2 protein level was increased in human ovarian tumor specimens and associated with poor prognosis." (PMID 36217544, 2022). "Second, the association between RSPO2 expression and clinical pathologic features of individuals could not be analyzed owing to the unavailability of sufficient paired ovarian tumor samples, and exploration with a large sample size is needed to further support this finding." (PMID 36217544, 2022). "Staining quantification showed that RSPO2 expression in ovarian tumor tissues was significantly higher than that detected in the paired normal tissues." (PMID 36217544, 2022). "Next, we investigated the molecular mechanisms by which RSPO2 activates FAK/Src signaling cascades in ovarian tumor cells." (PMID 36217544, 2022). "Based on the characteristic that RSPO2 is a secretory protein, we first established stable transfectants of RSPO2-overexpressing ovarian tumor cells by pooling G418-resistant clones." (PMID 36217544, 2022).
premature ovarian failure (1 paper, 2008). "Although RSPO2 ovarian localization and RSPO2 promoter studies are needed to assess a putative direct transcriptional activation of RSPO2 by FOXL2, RSPO2 can be considered as a good candidate gene for premature ovarian failure and XX sex-reversal in human." (PMID 18384673, 2008).
prostate tumors (1 paper, 2025). "In order to ascertain RSPO2’s relationship with AR, we investigated its role in primary prostate tumors (TCGA, n = 489) and observed RSPO2 alterations in 9% of samples." (PMID 40711886, 2025).
respiratory failure (1 paper, 2019). The significant impairment of gas exchange within the lungs resulting in hypoxia, hypercarbia, or both, to the extent that organ tissue perfusion is severely compromised. "Rspo2-deficient mice display distal limb loss and lung hypoplasia in embryos and die immediately after birth due to respiratory failure." (PMID 31109354, 2019).
thyroid cancer (1 paper, 2017). "In this study, we demonstrated that exogenous RSPO2 treatment increased GPR48/LGR4-dependent ERK activation in thyroid cancer cells." (PMID 29383135, 2017). "In parallel experiments, we observed that RSPO2 expression was also higher in the thyroid cancer cell lines (P<0.001)." (PMID 29383135, 2017). "Based on these findings, we speculate that exogenous RSPO2 treatment can induce increased ERK1/2 phosphorylation in thyroid cancer cells, and that the effect of RSPO2 is strongly dependent on expression of GPR48/LGR4." (PMID 29383135, 2017). "Moreover, treatment of thyroid cancer cells with exogenous R-spondin 2 induced activation of the β-catenin pathway through GPR48/LGR4." (PMID 29383135, 2017). "R-spondin 2, and GPR48/LGR4 were expressed at significantly higher levels in thyroid cancer than in normal controls." (PMID 29383135, 2017). "Based on this premise, we tested whether exogenous RSPO2 could directly increase β-catenin signaling, using a reporter assay and monitoring AXIN2 expression in control and GPR48/LGR4-knockdown thyroid cancer cells." (PMID 29383135, 2017).
tongue squamous cell carcinoma (1 paper, 2023). A squamous cell carcinoma that arises from the tongue. "Another essential finding regarding Rspo2 was that exogenous Rspo2 or overexpression of Rspo2 promoted proliferation in tongue squamous cell carcinoma." (PMID 37946278, 2023).
Tracheomalacia (1 paper, 2020). "Mutations in a number of other Wnt ligands or receptors expressed in the fetal foregut, including Wnt4, Wnt5a, Wnt7b, Ror2 and Rspo2, also display deficits in cartilage development with varying extents of tracheomalacia." (PMID 33328171, 2020).
tumor (48 papers, 2013 to 2026). "In a seminal study of 150 mCRPC patients, activating pathogenic RSPO2 structural rearrangements were identified, which led to gross overexpression of RSPO2 transcripts in the tumor." (PMID 40711886, 2025). "RSPO2 amplifications were associated with significant increases in tumor mutational burden (TMB) in both primary (p-value = 0.0030) and metastatic (p-value = 0.0048) PC patients." (PMID 40711886, 2025). "Loss-of-function mutations of the tumor-suppressor-like molecules Rnf43 and Znrf3 and elevated expression levels of the Wnt agonists Rspo2 and Rspo4 can also be counted among the prognostic biomarkers of breast cancer." (PMID 33585487, 2021). "Interestingly, we found that epigenetic reactivation of RSPO2 in the tumour context was associated with a significant impairment in cell viability in DLD1 and HCT116 cancer cell lines." (PMID 37612734, 2023). "Notably, the high expression of RSPO2 is positively associated with advanced clinical stages, tumor size, and metastasis." (PMID 33946652, 2021). "In conclusion, our study establishes RSPO2 as a clinically relevant prognostic marker with pro-tumor functions." (PMID 40711886, 2025). "RSPO2, which stimulates Wnt/β-catenin signaling, is another key contributor to tumor progression and metastasis." (PMID 40076569, 2025). "Based on an aggregate of 16 PC datasets consisting of 1051 tumors, RSPO2 amplifications (n = 104) were overrepresented in metastatic samples relative to primary tumor samples (54% vs. 28%, respectively)." (PMID 40711886, 2025). "After that, a group of primary tumor cells acquired six additional mutations (in genes AKT1, BCL9L, B2M, FBXW7, MUTYH, RSPO2)." (PMID 38685065, 2024). "Our observations indicate that tumour-mediated epigenetic repression and the subsequent epigenetic restoration of RSPO2 levels affects the cell viability status of CRC cell lines, further supporting previous data generated by Wu and colleagues." (PMID 37612734, 2023). "In 83% of T1 tumor samples, R-spondin-2, killer cell immunoglobulin-like receptor 2DL1, olfactory receptor 52R1, olfactory receptor 13C4, and inactive phospholipid phosphatase 7 were observed." (PMID 37761972, 2023). "Tumor tissue from nude mice from the experimental group displayed lower levels of Ki67 and RSPO2 expression than that from the control group, according to immunohistochemistry." (PMID 35281864, 2022). "A recent study showed that RSPO2 acts as a tumor suppressor in HCC by inhibiting the MAPK signaling pathway." (PMID 36217544, 2022). "The dysregulated expression of RSPO2 in tumor tissues inspired us to investigate its role in ovarian malignancy." (PMID 36217544, 2022). "Upregulated LGR4 protein expression was also confirmed in xenograft tumor samples with high RSPO2 expression." (PMID 36217544, 2022). "RSPO2 promotes a variety of biological processes involved in tumor progression by potentiating Wnt/β-catenin signaling." (PMID 36217544, 2022). "In contrast, Rspo2 appears to inhibit CRC metastasis by competing with the tumor-promoting Wnt5a for binding to Fz7 and thus antagonizing Wnt5a-driven non-canonical Wnt signaling." (PMID 33585487, 2021). "Studies in vivo showed that CGX1321 strongly reduced tumor growth in PDX mouse models harboring RSPO2 fusions after 28 days of treatment." (PMID 34771683, 2021). "Whereas, RSPO2 is indirectly correlated to affect immune response by activating Wnt/beta-catenin signaling regulating T cell-inflammation in the tumor microenvironment." (PMID 33504001, 2021). "In thyroid cancer, upregulation of the LGR4/RSPO2 pathway leads to tumor aggressiveness, promoting cell proliferation and migration through the Wnt/β-catenin pathway and MAPK/ERK1/2 signaling." (PMID 33946652, 2021).